PRPF31 (pre-mRNA processing factor 31)
Diseases named in the same sentence as PRPF31 in open-access papers (continued):
Sharing a sentence is not in itself a finding about the gene and the disease.
elliptocytosis (1 paper, 2012). "However, unlike erythropoietic protoporphyria and elliptocytosis, in PRPF31-linked adRP the molecular causes of such beneficial hyper-expression have remained, up to now, unexplained." (PMID 23144630, 2012).
juvenile macular degeneration (1 paper, 2019). "Although RP phenotype is predominantly associated with PRPF31 mutations in humans, some affected individuals developed juvenile macular degeneration apart from the typical RP phenotype, as described in two Chinese families carrying different mutations in the PRPF31 gene." (PMID 31892304, 2019).
leukemia (1 paper, 2022). A malignant (clonal) hematologic disorder, involving hematopoietic stem cells and characterized by the presence of primitive or atypical myeloid or lymphoid cells in the bone marrow and the blood. "TFPT (FB1), the nearest one adjacent to PRPF31, is reported to be related to development of leukemia, acting as a molecular fusion partner of TCF3 (E2A)." (PMID 36431159, 2022).
lung adenocarcinoma (1 paper, 2025). A carcinoma that arises from the lung and is characterized by the presence of malignant glandular epithelial cells. "In the TCGA lung adenocarcinoma cohort, PPP2R1A expression demonstrated significant positively correlated with PRPF31 (R = 0.72), SCAF1 (R = 0.72), and PTOV1 (R = 0.71)." (PMID 41409293, 2025).
macular cysts (1 paper, 2021). "The presence of macular cysts and the retinal phenotype observed in affected twins is more consistent with the phenotype associated with PRPF31 than with PRPF8." (PMID 34662339, 2021).
night blindness (1 paper, 2012). Inability to see clearly in dim light. "Patients carrying mutations in the PRPF31 gene in this study demonstrated classic RP with night blindness as the initial symptom, followed by the gradual constriction of the visual field and a decline in visual acuity later in life." (PMID 23288994, 2012).
ovarian carcinoma (1 paper, 2010). A malignant neoplasm originating from the surface ovarian epithelium. "As two other PRPF31 haplotypes were associated with ovarian cancer risk at p<0.10 (00111101 OR 2.81, 95% CI 0.85–9.22, p = 0.09; 10101101 OR 2.86, 95% CI 0.94–8.71, p = 0.06), other variants in the gene may also contribute to the observed global haplotype association." (PMID 20111712, 2010). "Of genes examined in relation to risk of invasive ovarian cancer and risk of invasive serous ovarian cancer, only global variation in the MSL1 and PRPF31 genes was associated at p<0.05." (PMID 20111712, 2010).
Retinal (1 paper, 2020). "The exonic deletion variant of over 52 kb in length in the PRPF31 gene that spanned exons 1 to 9 out of a total of 14 exons was identified by a gene panel (Retinal Dystrophy Xpanded Test of 880 genes, GeneDx)." (PMID 32000842, 2020).
Usher syndrome (1 paper, 2023). A syndromic diseae characterized by the association of sensorineural deafness (usually congenital) with retinitis pigmentosa and progressive vision loss. "During this process, SANS interacts with the U4/U6 and U5 snRNP-specific proteins PRPF31 and PRPF6 and regulates splicing, which is disturbed by variants of USH1G/SANS causative for human Usher syndrome (USH), the most common form of hereditary deaf–blindness." (PMID 38139438, 2023).
Retinopathy (4 papers, 2012 to 2022). "To validate the novel genetic testing tool for retinal disorders, we used four DNA samples from families, in which we had previously identified different types of mutations by Sanger sequencing: one 1 bp duplication and one 1 bp deletion in PRPF31 and missense mutations in TRPM1 and BEST1." (PMID 22277662, 2012). "The models developed here progress faster and have more severe retinopathy than what is observed in human patients, likely due to the complete KO of Prpf31 in AAV-infected retinal cells." (PMID 36509783, 2022). "Of the 14 differentially spliced and expressed proteins, PRPF31 itself was identified, in addition to superoxidase dismutase mitochondrial protein (SOD2) for which reduced expression has been linked to retinopathies." (PMID 30315276, 2018).
genetic diseases (2 papers, 2020 to 2022). "For some genetic diseases, such as autosomal-dominant RP caused by mutations in PRPF31, the disease mechanism involves a dominant-negative effect plus haploinsufficiency, and the silencing of the mutated allele along with the required dose of the gene may be required to obtain a therapeutic effect." (PMID 35456263, 2022).
PRPF31 also shares sentences with these, for which no sentence is quoted: cancer (2 papers); Leber congenital amaurosis (2); acrofacial dysostosis (1); age-related macular degeneration (1); amblyopia (1); Bietti crystalline dystrophy (1); cerebrocostomandibular syndrome (1); choroideremia (1); degenerative disease of (1); diabetes mellitus type 2 (1); DiGeorge syndrome (1); erythropoietic protoporphyria (1); Fanconi anaemia (1); glioblastoma (1); hyperopia (1); microphthalmia (1); Nager syndrome (1); serous ovarian cancer (1); syndromic (1); type 2 diabetes (1).